MEF2B (myocyte enhancer factor 2B)
Description:
Transcriptional activator which binds specifically to the MEF2 element, 5'-YTA[AT](4)TAR-3', found in numerous muscle-specific genes. Activates transcription via this element. May be involved in muscle-specific and/or growth factor-related transcription.
Synonyms: RSRFR2; LOC729991-MEF2B; MEF2BNB-MEF2B; BORCS8-MEF2B
Tractability: Small molecule: a structure with a bound ligand is known. PROTAC: ubiquitination databases record sites on it.
Gene: Protein-coding gene on chromosome 19 (19,145,567 to 19,192,131, reverse strand). Ensembl gene ENSG00000213999.
Subcellular location: Nucleus
Subcellular location (Human Protein Atlas): Cytosol; Nucleoplasm; Cell Junctions
Pathways (Reactome):
Developmental Biology: Myogenesis
Gene Ontology:
Molecular function: DNA-binding transcription activator activity, RNA polymerase II-specific; histone deacetylase binding; protein binding; RNA polymerase II cis-regulatory region sequence-specific DNA binding; sequence-specific double-stranded DNA binding; DNA-binding transcription factor activity; DNA-binding transcription factor activity, RNA polymerase II-specific; DNA binding; protein dimerization activity; RNA polymerase II transcription regulatory region sequence-specific DNA binding
Biological process: positive regulation of transcription by RNA polymerase II; cell differentiation; heart development; muscle organ development; animal organ development
Cellular component: transcription regulator complex; chromatin; nucleus
Genetic constraint (gnomAD): Loss-of-function variants: 14 observed, 28.13 expected, observed/expected ratio (o/e) 0.5, 90% interval 0.33 to 0.78. The upper end of that interval is the gene's LOEUF score, 0.78, which puts it in group 3 of 6, group 1 being the genes least tolerant of losing a copy. Missense variants: 390 observed, 428.51 expected, observed/expected ratio (o/e) 0.91, 90% interval 0.84 to 0.99. Synonymous variants: 177 observed, 181.67 expected, observed/expected ratio (o/e) 0.97, 90% interval 0.86 to 1.1.
Homologues: Orthologues: chimpanzee MEF2B (99% identical), macaque BORCS8 (98% identical), pig MEF2B (91% identical), dog MEF2B (90% identical), guinea pig MEF2B (70% identical), mouse Mef2b (68% identical), rat Mef2b (68% identical), zebrafish mef2b (42% identical). Paralogues in human: MEF2D (43% identical), MEF2C (43% identical), MEF2A (40% identical), SRF (18% identical).
Diseases named in the same sentence as MEF2B in open-access papers:
MEF2B is named in the same sentence as 48 diseases in open-access papers, as found by Europe PMC text mining. Sharing a sentence is not in itself a finding about the gene and the disease. The quoted sentences say what the papers report.
diffuse large B-cell lymphoma (11 papers, 2015 to 2026). "In support of this, increased MEF2B expression was shown to be associated with several B-cell malignancies, including diffuse large B-cell lymphoma (DLBCL), a frequently EBV infected B-cell neoplasm." (PMID 38530845, 2024). "MEF-2B acts as a transcriptional activator and is mutated in 11% of Diffuse large B-cell lymphomas (DLBCL), and 12% of follicular lymphomas." (PMID 31105874, 2019). "In addition, FL (follicular lymphoma) and DLBCL (diffuse large B-cell lymphoma) frequently have mutations in MEF2B, a transcription factor that is highly concentrated in germinal center-specific super enhancers." (PMID 39838405, 2025). "Mutations in the transcription factor MEF2B are found in diffuse large B-cell lymphoma." (PMID 26245647, 2015). "MEF2B is the target of heterozygous somatic non-synonymous and indel mutations in 8 to 18% of diffuse large B-cell lymphoma (DLBCL), 13% of follicular lymphoma (FL) and 3 to 7% of mantle cell lymphoma (MCL)." (PMID 26506234, 2016). "Previous research in diffuse large B‐cell lymphoma has shown that MEF2B directly activates the transcription of BCL6 in germinal center (GC) B cells." (PMID 39931830, 2025). "MEF2B, another member of the MEF2 family, has been found to be mutated in ca. 11% of diffuse large B cell lymphoma (DLBCL), which are GC-derived tumors." (PMID 30233601, 2018). "A similar effect has been demonstrated in multiple diffuse large B-cell lymphoma cell lines, where knockdown of MEF2B led to down-regulation of BCL6 expression and repression of cell growth." (PMID 30514247, 2018). "Myocyte enhancer factor 2B (MEF2B) is a transcription factor with mutation hotspots at K4, Y69 and D83 in diffuse large B-cell lymphoma (DLBCL)." (PMID 26245647, 2015). "Since MEF2B is a known regulator of BCL6 in normal GC B-cells, diffuse large B-cell lymphoma, and follicular lymphoma, we subsequently focused on the effect of MEF2B knockdown on BCL6." (PMID 41992423, 2026). "BCL6 and MEF2B (member of the MEF cluster) are both crucial regulators of B-cell development, and changes in their COF interactions have been implicated in diffuse large B-cell lymphoma (DLBCL)." (PMID 39166482, 2024).
lymphoma (9 papers, 2015 to 2024). A malignant (clonal) proliferation of B- lymphocytes or T- lymphocytes which involves the lymph nodes, bone marrow and/or extranodal sites. "In lymphoma, the frequently mutated transcriptional activator MEF2B exhibits N-terminal hotspot mutations at regulatory residues." (PMID 37415185, 2023). "MEF-2B is a target for somatic mutations in various lymphomas, most of these affecting the MADS-box/MEF-2 domain, and the most frequent being the D83V mutation in cancer." (PMID 31105874, 2019). "We next investigated how the activity of MEF2B is altered by the MEF2B hotspot mutations identified in lymphoma, K4E, Y69H and D83V." (PMID 26245647, 2015). "However, MEF2B was the only MEF2 family member strongly implicated in lymphoma development, indicating that its distinct features are relevant to human disease." (PMID 26506234, 2016). "Additional findings included MEF2B positivity, confirming the lymphoma diagnosis, and an immunoglobulin gene rearrangement, which demonstrated a monoclonal B-cell population consistent with a neoplastic process." (PMID 39840177, 2024). "These allow the MEF2B D38V mutant to evades repressor binding and, in turn, bind lymphoma-promoting genes." (PMID 37415185, 2023). "In particular, mutations in MEF2B, the most divergent and least studied protein of the MEF2 family, promote lymphoma development." (PMID 29674676, 2018). "Other MEF2 proteins were much less commonly affected in lymphoma, indicating that MEF2B has a role unique from its paralogs in the B-cells from which these lymphomas arise." (PMID 26506234, 2016). "We also describe effects of MEF2B mutation on both DLBCL cell chemotaxis and the expression of lymphoma driver genes." (PMID 26245647, 2015). "The MEF2B positivity, a marker typically associated with lymphoma rather than reactive hyperplasia, confirmed the neoplastic nature of the lesion." (PMID 39840177, 2024). "In an extensive analysis of various B and T-cell lymphomas to validate MEF-2B as an immunohistochemical marker, the expression revealed a statistically significant association with BCL6 in DLBCL and indicates MEF-2B as a valuable marker for differential diagnosis of various types of lymphomas." (PMID 31105874, 2019). "Mutations in the NFAT genes, their targets, and genes involved in the calcium-induced activation of the NFAT and MEF2B pathways are novel and previously not reported aberrations in MZ and other lymphomas." (PMID 35528192, 2021). "In our study, we included KMT2D, CREBBP, EZH2, EP300, MEF2B, and TET2 in our lymphoma panel." (PMID 31403034, 2019).
B-cell lymphomas (6 papers, 2015 to 2026). "It remains to be established whether mutant MEF2B can drive HDAC9 expression in B-cell lymphomas, but recent research has identified a novel MEF2D–BCL9 fusion protein associated with high-risk acute B-cell precursor lymphoblastic leukemia (ALL) that directly upregulates HDAC9." (PMID 27799148, 2016). "We observed a strong decrease in BCL6 at the RNA and protein level in BL and showed a strong correlation between MEF2B and BCL6 transcript levels in a panel of B-cell lymphoma cell lines, primary BL samples, and normal B-cell subsets." (PMID 41992423, 2026).
non-Hodgkin lymphoma (4 papers, 2015 to 2025). Distinct from Hodgkin lymphoma both morphologically and biologically, non-Hodgkin lymphoma (NHL) is characterized by the absence of Reed-Sternberg cells, can occur at any age, and usually presents as a localized or generalized lymphadenopathy associated with fever and weight loss. "In various forms of non-Hodgkin lymphoma, the most frequent mutation (D83V) of human protein myocyte enhancer factor 2B (MEF2B) induces an α-helix to β-sheet fold switch." (PMID 40709301, 2025). "In particular, MEF2B, the most divergent and least studied protein of the MEF2 family, has a role unique from its paralogs in non-Hodgkin lymphomas." (PMID 26506234, 2016).
diabetic cardiomyopathy (3 papers, 2021 to 2025). Diabetic cardiomyopathy is a disorder of the heart muscle in people with diabetes. "Previous study has shown that YB-1 can target the MEF2B promoter region to inhibit its expression and improve diabetic cardiomyopathy." (PMID 36588134, 2023).
lung carcinoma (2 papers, 2016 to 2021). "However, studies have found that MEF2B can activate the β-catenin pathway to induce lung cancer cell invasion." (PMID 34233659, 2021). "In addition, MEF2B knockdown reduced EGF-induced DDIAS expression in lung cancer cells." (PMID 27660814, 2016).
virus infection (2 papers, 2021 to 2024). "First, MEF2B is critical for the formation of germinal centers and promoting early B-cell development, while B cells are essential in the defense of virus infection by producing protective antibodies." (PMID 34465887, 2021). "Existing studies have shown that STMN1 plays an important role in viruses infection, and low expression of STMN1 inhibits dengue viruses replication; In addition, miR-760-3p regulates decreased expression of MEF2B and CDC25B." (PMID 38178220, 2024).
autoimmune disease (1 paper, 2025). A disorder resulting from loss of function or tissue destruction of an organ or multiple organs, arising from humoral or cellular immune responses of the individual to their own tissue constituents. "ZEB2 is essential for age-associated B cell accumulation and function by repressing MEF2B and Itgax, presenting as a powerful driver for B cell autoimmunity and a potential target for intervention in autoimmune disease." (PMID 40510028, 2025).
bone tumors (1 paper, 2023). "In bone tumors, the MSKCC cohort had significantly fewer mutations in MAP3K1, CREBBP, MCL1, GNAQ, MEF2B, MYCN, SDHA, and SMARCA4." (PMID 37546405, 2023).
cardiac hypertrophy (1 paper, 2021). "Recent study has reported that MEF2B promotes mitochondrial dysfunction, thus accelerating cardiac hypertrophy and heart failure." (PMID 34778410, 2021).
clear cell renal cell carcinoma (1 paper, 2025). "We constructed a multi-gene risk prediction model incorporating IGF2BP3, CENPA, and MEF2B to evaluate the prognostic predictive power of these three key genes in clear cell renal cell carcinoma (KIRC)." (PMID 41589308, 2025).
COVID-19 (1 paper, 2021). A disease caused by infection with severe acute respiratory syndrome coronavirus 2. "We identified common variants in ABO and FOXP4-AS1 and a rare variant in MEF2B to be significantly associated with COVID-19 severity, likely through regulation of the adaptive immunity." (PMID 34465887, 2021). "The rare risk variant in MEF2B, on the other hand, is specific to East Asians and confers about the eightfold increase in the risk of severe COVID-19 among carriers." (PMID 34465887, 2021). "Importantly, MEF2B is overexpressed in lymphocytes 28 and plays critical roles in anti-virus immune which would be associated with COVID-19 development and severity." (PMID 34465887, 2021). "Our analyses lead to three significant loci predisposing risk to severe COVID-19, including an intronic variant in FOXP4-AS1, a frameshift insertion in ABO, and a Chinese-specific rare intronic variant in MEF2B." (PMID 34465887, 2021).
gastric cancer (1 paper, 2021). A primary or metastatic malignant neoplasm involving the stomach. "In addition, using The Human Protein Atlas (HPA) to analyze the protein expression of hub TFs, ELK3 immunohistochemical staining intensity in normal tissues is lower than gastric cancer tissues, while ZNF300 and MEF2B are higher than gastric cancer tissues." (PMID 34233659, 2021). "The results suggested that the expression of ELK3 and SP6 is increased in gastric cancer, and the expression of ZNF300 and MEF2B is down-regulated in gastric cancer." (PMID 34233659, 2021).
Hodgkins lymphoma (1 paper, 2023). A heterogeneous group of malignant lymphoid neoplasms of B-cell origin characterized histologically by the presence of Hodgkin and Reed-Sternberg (HRS) cells in the vast majority of cases. "MEF2B expression was noted in 100% of the NLPHL cases, and Hodgkin Reed Sternberg cells of classic Hodgkin lymphoma were almost always negative for MEF2B expression." (PMID 37206275, 2023).
Intellectual disability (1 paper, 2016). "The only non-cancer disease or disorder in which MEF2B alterations may be implicated is intellectual disability, based on the weak evidence that MEF2B was co-deleted with 10 or 75 other genes in two patients with intellectual disability." (PMID 26506234, 2016).
latent infection (1 paper, 2020). "Its constituent MEF2B was reported to be a target of Epstein-Barr Virus proteins and plays a role in the survival of virus-infected B-cells maintaining latent infection." (PMID 33362776, 2020).
leukemia (1 paper, 2022). A malignant (clonal) hematologic disorder, involving hematopoietic stem cells and characterized by the presence of primitive or atypical myeloid or lymphoid cells in the bone marrow and the blood. "For example, we find that increased dependency on BCL2 is associated with leukemia, myeloma, and MEF2B mutations." (PMID 35382456, 2022). "SuperDendrix also finds associations for three downstream targets of TCF3 and IRF4 transcription factors: BCL2 and {leukemia, myeloma, MEF2B(A)}, PIM2 and myeloma, and POU2AF1 and Myeloma,MEF2BA." (PMID 35382456, 2022).
liver fibrosis (1 paper, 2016). "MEF2B and its gene family members play an important role in cell proliferation and differentiation, embryonic development, muscle production, neural system differentiation and liver fibrosis." (PMID 27472808, 2016).
lung adenocarcinoma (1 paper, 2025). A carcinoma that arises from the lung and is characterized by the presence of malignant glandular epithelial cells. "Furthermore, we analyzed the expression of RUNX3, IKZF1, and MEF2B in lung adenocarcinoma and normal lung tissues using TCGA data, and the analysis indicated that the three transcription factors were all downregulated in lung adenocarcinoma tissues." (PMID 40068093, 2025).
ulcerative colitis (1 paper, 2023). An inflammatory bowel disease involving the mucosal surface of the large intestine and rectum. "It has been shown that MEF2B is significantly up-regulated in ulcerative colitis and is a biomarker for the treatment of ulcerative colitis." (PMID 36983731, 2023).
tumor (13 papers, 2013 to 2025). "The ancestor tumor cells harbored IGH-CCND1 translocations and MEF2B mutations, which gave rise to divergent clones via the acquisition of additional mutations." (PMID 40876452, 2025). "Given that IGF2BP3 is known to influence this microenvironment, we are analyzing prognostic models’ impact on KIRC immunity to assess the roles of IGF2BP3, CENPA, and MEF2B axis as a whole factor in tumor immunity." (PMID 41589308, 2025). "The expression of IgD and MEF2B in the tumor cells is very helpful to confirm the diagnosis of NLPHL vs. CHL, especially in needle biopsies." (PMID 39707053, 2025). "Factors secreted by RENCA macrobeads significantly up-regulated the activity of the MEF2 transcription factor as well as altered the transcription of MEF2b and MEF2d isoforms in targeted tumor cells." (PMID 30514247, 2018). "Hypermethylation of genes such as MEF2B, involved in neuronal differentiation, could contribute to increased tumor invasiveness." (PMID 40640872, 2025). "In GBs, aberrant methylation of MEF2B may inhibit critical pathways that regulate cell proliferation and apoptosis, potentially leading to increased invasive capacity of tumor cells." (PMID 40640872, 2025). "In addition, recent tumor analysis has demonstrated that DLBCL and FL share somatic mutations in the same chromatin and histone modifying genes, MLL2 and MEF2B, respectively." (PMID 23349640, 2013). "Tumour infiltrating lymphocyte and myeloid populations were enriched for motifs including ETS family transcription factors (ETV5/6 and EHF) and MEF2B, as well as NFKB1 which is a central activator of pro-inflammatory genes." (PMID 39341888, 2024). "MEF2B, MEF2C, and MEF2D are predominantly involved in tumor proliferation, migration, and invasion and in tumor immunity." (PMID 33863999, 2021). "The development and survival of tumor cells depend on the involvement of the MEF2 (Myocyte Enhancer Factor 2) family, which includes MEF2A, MEF2B, and MEF2D; these TFs are involved in signaling pathways that regulate cellular homeostasis and metabolic adaptation." (PMID 41155227, 2025). "Both EGR2 and MEF2B are regulators of cell transcription, and the former was reported to be involved in the epithelial-mesenchymal transition (EMT) pathway, while the latter was differentially expressed between primary tumors and nodal metastasis tumor in HNSCC." (PMID 34504787, 2021). "The function of MEF2B mutation in DLBCL has not been definitively established, and these putative inactivating mutations provides further evidence of its role as a tumour suppressor but does not eliminate the possibility of shortened isoforms with an enhanced or distinct activity." (PMID 30275490, 2018). "The tumor cells show a B-cell phenotype with expression of the transcription factors BOB1 and OCT2 and often a non-GCB phenotype with lack of CD10 expression but expression of MUM1, BCL6, and MEF2B." (PMID 39707053, 2025).
cancer (9 papers, 2015 to 2023). A tumor composed of atypical neoplastic, often pleomorphic cells that invade other tissues. "MEF-2B is widely implicated in cancer phenotypes and poor prognosis based on its mutations and the pathways it regulates." (PMID 31105874, 2019).
MEF2B also shares sentences with these, for which no sentence is quoted: follicular lymphoma (5 papers); mantle cell lymphoma (3); Burkitt lymphoma (2); ovarian carcinoma (2); acute B-cell precursor lymphoblastic leukemia (1); adrenocortical carcinomas (1); astrocytoma (1); Autoimmunity (1); B-cell neoplasm (1); breast carcinoma (1); cardiomyopathies (1); colorectal cancer (1); heart failure (1); hepatocellular carcinoma (1); immune diseases (1); MALT lymphoma (1); marginal zone lymphoma (1); meningioma (1); mycosis fungoides (1); myeloma (1); neuroblastoma (1); sarcoma (1); splenic marginal zone lymphoma (1); T-cell lymphomas (1); thymoma (1); uterine carcinoma (1).